INSR (insulin receptor)
Diseases named in the same sentence as INSR in open-access papers (continued):
Sharing a sentence is not in itself a finding about the gene and the disease.
Insulin resistance (continued). "Such processes are totally or partially compromised in type 2 diabetes, due to the development of insulin resistance, which is mainly based on the desensitization of the insulin receptor and impaired phosphorylation of its substrates." (PMID 26075283, 2015). "In this study, we used the RYGB surgery to explore the role of the liver INSR isoforms in the pathology of insulin resistance." (PMID 25742416, 2015). "To further confirm that insulin resistance was relieved in these cells, we examined the expression of genes involved in insulin resistance (INSR, CREB, CRTC, IGFBP-1, and GLUT2)." (PMID 26077338, 2015). "Yi reported that under the condition of insulin resistance induced by S961 (an insulin receptor antagonist), hepatic betatrophin mRNA expression was upregulated and correlated with high pancreatic beta cell proliferation rates." (PMID 26247824, 2015). "Future studies are necessary to confirm that the insulin receptor and glucose transporters, which are related to insulin resistance, are indeed functionally inhibited by GON-1 depletion." (PMID 26218657, 2015). "Fatty acids promote insulin resistance via suppressing insulin signaling by stimulating serine protein kinases that phosphorylate insulin receptor substrates (IRS) and disrupt the downstream transduction of signal from the insulin receptor." (PMID 26221589, 2015). "It has further been suggested that proinflammatory cytokines can contribute to development of insulin resistance directly by modulation of the insulin receptor in periphery tissues." (PMID 26457080, 2015). "Glycogen synthase kinase 3 (GSK3) α and β were also detected, since there is evidence suggesting that GSK3 contributes to the induction by insulin resistance independently of insulin receptor signaling or PI3K-AKT activity." (PMID 25993471, 2015). "Based on prior work demonstrating that TNFα activates SOCS3 and SOCS3 can induce insulin resistance through activation of insulin receptor via phosphorylation on tyrosine 960, we measured both SOCS3 and IRTyr960 in the lean and obese animals." (PMID 25874611, 2015). "The B2R is known to ameliorate insulin resistance by increasing glucose uptake and supply, and by inducing glucose transporter-4 translocation either directly or through phosphorylation of insulin receptor." (PMID 26413386, 2015). "Insulin resistance is present in the majority of PCOS cases with linkage and association between single nucleotide polymorphisms of insulin receptor (INSR) gene and PCOS." (PMID 25114673, 2014). "Dysfunctional regulation of signaling pathways downstream of the insulin receptor plays a pivotal role in the pathogenesis of insulin resistance and type 2 diabetes." (PMID 25071716, 2014). "Increased phosphorylation of IRS-1 would be expected to directly inhibit binding of the insulin receptor to IRS-1 and thus block normal insulin stimulation of its receptor, causing insulin resistance." (PMID 25352752, 2014). "Certainly cerebral insulin resistance is present in AD just as in T2D, and the appropriate alterations in post-insulin receptor intracellular signalling have been impressively demonstrated in fresh AD autopsy brains." (PMID 25231068, 2014). "TNFα is known to induce insulin resistance in rodents and decrease the expression of insulin receptor, IRS-1, and GLUT4 in 3T3-L1 adipocytes." (PMID 24918199, 2014). "The liver-specific glucokinase knockout mouse experienced long-term hyperglycemia, which results in decreased insulin receptor levels and ultimately leading to insulin resistance and attenuated glucose uptake." (PMID 24447392, 2014). "Unlike glucose, fructose induced metabolic syndrome is attributed mainly to the effect of fructose on insulin receptor phosphorylation while glucose induced metabolic syndrome is attributed to the higher insulin release and development of insulin resistance." (PMID 25045706, 2014).
Insulin resistance (continued). "Compared with ApoE-/- mice, TRAIL-/-ApoE-/- mice displayed insulin resistance and type-2 diabetic features with reduced renal insulin-receptor expression." (PMID 24667560, 2014). "Previous studies found that in spite of severe insulin resistance, muscle insulin receptor and GLUT4 expression were normal." (PMID 25472611, 2014). "In profoundly insulin resistant ob/ob animals, cinnamon promoted tyrosine phosphorylation of the insulin receptor in liver tissues (insulin-stimulated PY-IR: 61.3±3.3 vs. 35.4±5.3 arb." (PMID 24643026, 2014). "This is true for TNF-α, which acts on the insulin receptor and prevents the dephosphorylation of insulin receptor substrates, thus blocking receptor signaling and preventing glucose entry into the cell (insulin resistance)." (PMID 24527464, 2014). "Insulin resistance in metabolic syndrome subjects is profound in spite of muscle insulin receptor and insulin‐responsive glucose transporter (GLUT4) expression being nearly normal." (PMID 25472611, 2014). "The potential effect of IGF1R antibodies on INSR signaling is of special concern, given that these antibodies can co-target or alter INSR function, leading to insulin resistance and adverse effects on glucose and carbohydrate metabolism." (PMID 24904527, 2014). "Previously, it was shown that chronic exposure to TNF-α decreased insulin receptor phosphorylation in adipocytes and that increased levels of TNF-α, IL-6 and IL-1β are linked to systemic inflammation and accompany insulin resistance." (PMID 23915208, 2013). "TNF-α is markedly upregulated in obese states and probably promotes insulin resistance by interfering with insulin receptor signalling." (PMID 23671875, 2013). "At a more direct level, those who have a defect in their insulin receptor have very high levels of insulin resistance and frequently develop diabetes from compensatory beta cell exhaustion, yet are protected from fatty liver and atherogenic dyslipidemia." (PMID 23766565, 2013). "TNF-α also induces serine phosphorylation of IRS1 to modulate the downstream effectors of the insulin receptor resulting in insulin resistance." (PMID 23781214, 2013). "Syndrome of extreme insulin resistance (SEIR) is a rare spectrum disorder with a primary defect in insulin receptor signalling, noted primarily in children, and is often difficult to diagnose due to the clinical heterogeneity." (PMID 23367497, 2013). "TNF-α is an important mediator of insulin resistance in obesity and diabetes through its ability to decrease the tyrosine kinase activity of the insulin receptor." (PMID 23533500, 2013). "Several studies suggest that insulin resistance in PCOS patients is the result of a defect in INSR signaling." (PMID 24639745, 2013). "The most common group of patients with monogenic insulin resistance have a mutation in the insulin receptor (INSR), leading to a global reduction of insulin receptor function in target cells." (PMID 23766565, 2013). "One important link between AD and T2DM is insulin resistance in the CNS due to alterations in insulin receptor sensitivity and insulin signaling transduction." (PMID 23829668, 2013). "This idea is supported by a recent study that reported a significant decrease in insulin receptor mRNA in cultured DRG neurons that displayed insulin resistance when treated with high levels of insulin." (PMID 24252636, 2013). "It provides a direct molecular link between mitochondrial dysfunction and derangements in insulin receptor signalling and insulin resistance." (PMID 23730255, 2012). "For instance, TNF-α an inducer of insulin resistance have been shown to directly affect the insulin receptor." (PMID 23272222, 2012). "TNF-α has been considered as a key mediator of obesity-related insulin resistance because of its increased expression in obesity and its inhibitory effect on insulin receptor signaling." (PMID 22615828, 2012).
Insulin resistance (continued). "A decrease in insulin receptor signaling mediates reduced responsiveness of tissues or cells to insulin, i.e., insulin resistance, which is central for development of metabolic syndrome and type-II diabetes." (PMID 22934083, 2012). "A switch from a tyrosine phosphorylation to a serine phosphorylation of the insulin receptor substrate (IRS) family of proteins impairs the metabolic activity of insulin leading to insulin resistance and type 2 diabetes." (PMID 22701480, 2012). "Strong evidence suggests that muscle accumulation of diacylglycerol and long chain acyl-CoA leads to insulin resistance through the activation of serine protein kinase C, which impairs insulin receptor and IRS-1 tyrosine phosphorylation." (PMID 22359625, 2012). "Alternative splicing of insulin receptor (IR) contributes to insulin resistance, whereas alternative splicing of a muscle-specific chloride channel (ClC-1) leads to myotonia." (PMID 22453899, 2012). "Members of the suppressor of cytokine signaling (SOCS) family of proteins inhibit tyrosine kinase receptor signaling and are known to attenuate the insulin receptor and induce adipose insulin resistance." (PMID 22709547, 2012). "It is possible that the same triggers to autoimmune RF and ACPA production also contribute to insulin receptor antibodies sufficient to induce the degree of insulin resistance that we see in our study." (PMID 21959060, 2011). "Defects in phosphorylation of the insulin receptor and its substrates have an important role in insulin resistance." (PMID 22249794, 2011). "Inflammatory cytokines such as TNF, IL-6 and MCP-1 have been also shown to inhibit insulin action through modification of signaling properties of insulin receptor substrates, contributing to liver and skeletal muscle insulin resistance." (PMID 21789167, 2011). "While severe insulin resistance secondary to insulin receptor antibodies in the context of type I diabetes mellitus is widely recognized, there are limited published data describing the association of insulin resistance with other autoantibodies." (PMID 21959060, 2011). "Gene variants related to insulin resistance such as insulin gene (VNTR), insulin receptor (INSR), insulin receptor substrate proteins (IRS1/2) and calpain-10 have shown to be associated with PCOS and related metabolic abnormality." (PMID 21492415, 2011). "Down-regulation of the insulin receptor (IR) protein levels in insulin-target tissues such as liver, skeletal muscle, and adipose tissue has been shown to correlate with insulin resistance." (PMID 21957486, 2011). "Ectonucleotide pyrophosphatase phosphodiesterase 1 (ENPP1) is a class IItransmembrane glycoprotein, which inhibits insulin receptor (IR) signaling and whichhas been, therefore, proposed as a candidate for insulin resistance." (PMID 21573217, 2011). "Activation of PRKCA mediates serine/threonine phosphorylation of the insulin receptor resulting in decreased active form of insulin receptor, inducing insulin resistance." (PMID 21689475, 2011). "Hepatic insulin resistance has been closely examined in the LIRKO (liver-insulin receptor knock-out) mouse as this represents the ultimate model of insulin resistance in the liver." (PMID 22087313, 2011). "However, it has been demonstrated that insulin resistance associated with obesity largely stems from posttranslational modifications of insulin signaling proteins, such as inhibitory serine phosphorylation of the insulin receptor or its downstream signaling mediators." (PMID 20463885, 2010). "Inflammatory cytokines like TNFα, can act as mediators of insulin resistance by impairing the tyrosine kinase activity of both the insulin receptor (IR) and insulin receptor substrate (IRS-1), thus inhibiting insulin signaling." (PMID 20634940, 2010). "Numerous studies have demonstrated that TNF-α limits insulin receptor signaling and promotes insulin resistance." (PMID 20808947, 2010).
Insulin resistance (continued). "Hepatic insulin resistance is caused by alterations in substrate 1 (IRS-1) and substrate 2 (IRS-2) of the insulin receptor." (PMID 20946638, 2010). "Possible subcellular mechanisms of insulin resistance were investigated by performing analysis of insulin receptor and post receptor signaling in skeletal muscle biopsy." (PMID 19941665, 2009). "This resulted in the insulin resistance marked by the down-regulation of insulin receptor signalling (Irs1, Foxo1, and Foxo3a), and down-regulation of Glut4." (PMID 19344534, 2009). "Excessive NO leads both to nitrosylation and inactivation of the insulin receptor and Akt, increasing insulin resistance." (PMID 18335029, 2008). "Studies indicate that insulin resistance can be induced by stimulating the degradation of important molecules in the insulin signaling pathway, in particular the insulin receptor substrate proteins IRS1, IRS2 and the kinase AKT1 (Akt)." (PMID 19007436, 2008). "Abnormal responses of insulin receptor mRNA levels to high salt intake were reported in kidneys and livers of animal models of insulin resistance such as the spontaneously hypertensive rats (SHR) and the fructose-fed rats." (PMID 18570670, 2008). "Protein tyrosine phosphatases (PTPases) have been suggestedto modulate the insulin receptor signal transduction pathways.Westudied PTPases in Psammomys obesus, an animal model of nutritionallyinduced insulin resistance." (PMID 12458663, 2002). "Furthermore, Aβ promotes the degradation of INSR in brain capillaries and competes with insulin for binding to INSR to block INSR signalling, collectively contributing to insulin resistance in AD." (PMID 41566484, 2026). "However, hydroxychloroquine has been reported to improve insulin resistance, enhance β-cell function, increase adiponectin, and augment insulin-receptor affinity." (PMID 41569989, 2026). "Insulin resistance is characterized by inactivation of the insulin-signaling pathway, primarily through serine phosphorylation of the insulin receptor substance, thereby disrupting the phosphatidylinositol 3-kinase/protein kinase B (PI3K/AKT) signaling cascade." (PMID 41590515, 2026). "The improvement of glycemic control and reduction of insulin resistance may be due to increased insulin receptor sensitivity resulting from the alkaline nature of the mineral water." (PMID 41378230, 2025). "DAGs are involved in the activation of protein kinase C (PKC), which may inhibit the insulin receptor via threonine 1160, an amino acid involved in reducing insulin resistance." (PMID 40429815, 2025). "Another potential mechanism by which Hcy levels may be relevant to maternal insulin resistance is through the modification of the immature form of the insulin receptor (pro-IR) via cysteine-homocysteinylation (C-Hcy) at the cysteine-825 residue." (PMID 40869296, 2025). "This, in turn, leads to insulin receptor degradation and promotes insulin resistance in obese mice." (PMID 39747658, 2025). "Furthermore, PFASs change systemic insulin resistance by altering insulin receptor signalling and adipokine synthesis, aggravating the pathogenesis of PCOS." (PMID 40724853, 2025). "However, during an acute insulin resistance induced by insulin receptor antagonist S961, glycine and β-alanine enhanced insulin secretion and reduced blood glucose levels by increasing β cell secretory capacity." (PMID 40260914, 2025). "Its exact prevalence has not been assessed, but recent data on congenital insulin resistance linked to insulin receptor gene mutations that include RMS and DS set the incidence at ≈1 in 1,200,000–1,300,000 live births." (PMID 40565151, 2025). "Such a dysregulation of alternative splicing espouses variable disease symptoms, including the mis-splicing of muscle-specific chloride channel (CLCN1), cardiac troponin T (TNNT2) and insulin receptor (IR) mRNAs, resulting in myotonia, cardiac defects, and insulin resistance, respectively." (PMID 39858595, 2025).
Insulin resistance (continued). "Disruption of insulin receptor function leads to insulin resistance in various tissues." (PMID 41155203, 2025). "IgG1, the most abundant subclass in the circulation and tissues, has the highest affinity for the insulin receptor ectodomain, and therefore could be the primary direct mediator of insulin resistance in obesity." (PMID 41425575, 2025). "A study had revealed that circulating mannose levels exhibit a positive correlation with obesity-independent insulin resistance, a relationship mediated by mannose-induced impairment of insulin receptor function or its participation in advanced glycation end product formation." (PMID 41373475, 2025). "In addition to the splicing abnormalities at the receptor level, increasing evidence suggests that defects in the post-insulin receptor signaling pathways also play a crucial role in insulin resistance in DM1." (PMID 41018201, 2025). "In a 2022 case study of treatment-resistant bipolar depression, reversal of insulin resistance with metformin was accompanied by restoration of blood–brain barrier integrity and full symptomatic remission, implicating brain insulin-receptor signalling in mood restoration." (PMID 41373485, 2025). "Computational docking studies further indicate that UA could interact with the insulin receptor (IR) and retinol-binding protein 4 (RBP4), suggesting a potential role in enhancing insulin receptor signaling and mitigating RBP4-associated insulin resistance." (PMID 41374004, 2025). "The term insulin resistance refers to decreased insulin receptor sensitivity." (PMID 41009753, 2025). "Moreover, ferulic acid derived from Hibiscus mutabilis mitigates fatty acid-induced insulin resistance by restoring insulin receptor expression, possibly via the upregulation of insulin receptor substrate-1 (IRS)-1." (PMID 40565007, 2025). "Notably, exosomes derived from lipid-dysregulated adipocytes carry miR-1 and miR-133 that target IRS-1 and INSR, thereby exacerbating insulin resistance." (PMID 41438998, 2025). "SMs modulate membrane microdomain structure, and their dysregulation may disrupt insulin receptor localization, thereby contributing to insulin resistance." (PMID 41239402, 2025). "As for the reason why time-restricted fasting improves insulin resistance, we believe that time-restricted fasting may have an activating effect on insulin receptor targets in skeletal muscle and related organs, which requires further study." (PMID 39925816, 2025). "Our studies reinforce AMPK as a direct upstream kinase that phosphorylates SREBP-1c to inhibit its nuclear translocation and transcriptional activity, ultimately suppressing hepatocyte lipogenesis and INSR degradation implicated in the rescuing from NAFLD and insulin resistance." (PMID 39747658, 2025). "Recent literature further suggests that the mechanisms for the association between T2D and high AD risk revolves around glucotoxicity, and its downstream consequences like insulin resistance, impaired insulin receptor signaling, advanced glycation end products, or inflammation." (PMID 39773760, 2025). "Magnesium is an important cofactor for a number of cellular functions related to insulin action and secretion, e.g., for the normal function of the insulin receptor, and it has been postulated that hypomagnesemia may contribute to insulin resistance." (PMID 39911868, 2025). "We hypothesized that patients with lower plasma magnesium would have higher insulin resistance, as the tyrosine kinase in the insulin receptor uses magnesium as a cofactor with adenosine-tri-phosphate." (PMID 39911868, 2025). "The role of hepatic PKCɛ in lipid-induced hepatic insulin resistance, particularly whether PKCɛ alone is responsible for phosphorylation of insulin receptor at Thr1160 in hepatocytes 33,34, 35, has been under debate." (PMID 39829776, 2025). "Moreover, STAT’s target gene is SOCS3, which inhibits insulin receptor signaling, which also results in insulin resistance." (PMID 41007818, 2025).